APC (APC regulator of Wnt signaling pathway)
Diseases named in the same sentence as APC in open-access papers (continued):
Sharing a sentence is not in itself a finding about the gene and the disease.
colorectal cancer (continued). "Both the APC gene and CTNNB1 are often mutated in colorectal cancers of non-FAP patients, and overexpression of constitutively active CTNBB1 or loss of APC function can result in colorectal tumorigenesis." (PMID 35207472, 2022). "Concerning the role of APC in sporadic CRC, with the gradual deepening of researches on colorectal cancer, various studies have shown that the aberrant methylation of APC gene has a non-negligible impact on the occurrence and development of sporadic CRC." (PMID 33968756, 2021). "Then, a thorough inquiry of the expression profile of APC was made using TIMER database, indicating that its mRNA expression was significantly decreased in enriched cancer types, such as breast cancer, colorectal cancer, lung squamous cell carcinoma, lung adenocarcinoma, etc." (PMID 33363011, 2020). "Moreover, the most popular genes were APC (in Wnt pathway), KRAS (in MAPK pathway) and PIK3CA (in PI3K pathway) in the colorectal cancer, pancreatic cancer, and gastric cancer while they were beta-catenin and CTNNB1 in liver cancer." (PMID 33127962, 2020). "In this study we observed that MEK inhibition further induced canonical WNT signaling in APC and KRAS mutant HCT-15 colorectal cancer cells, but not in APC mutant/KRAS WT COLO320DM cells." (PMID 30717152, 2019). "Note that the reference to APC-regulating PPARβ/δ, and the suggestion that relative expression is higher in colorectal cancer cell are no longer included in the NBCI description." (PMID 31602402, 2019). "Remarkably, however, expression of axin proteins above a certain threshold, e.g., by overexpression or stabilization by tankyrase inhibition suffices to degrade β-catenin in the absence of APC and blocks colorectal cancer proliferation." (PMID 31534175, 2019). "Overexpression of PR61α in the colorectal cancer HCA7 cell line (wild-type APC) but not the SW480 cell line (APC truncation at 1338) recapitulates the decreases in β-catenin observed in HEK293 cells." (PMID 29495399, 2018). "Our data indicate the possibility of such a negative effect of the substitution C > G (rs79896135) on APC expression in vivo and development of predisposition to FAP, and subsequently colorectal cancer." (PMID 28105931, 2016). "Aberrantly methylated levels of APC and MGMT were also observed in colorectal cancer tissues." (PMID 26862903, 2016). "Complete somatic inactivation of APC in discrete crypts of the intestinal epithelium appears to be the initial event of the tumorigenesis in Min/+ mice, human FAP and in the majority of sporadic colorectal cancer in humans." (PMID 28002446, 2016).
colorectal cancer (continued). "TACSTD2 was proposed to be a Wnt target identified through consistent gene expression changes in APC-mutant intestinal adenomas from humans and mice; EFNB1 :Eph-related receptor is a Wnt signalling target gene in colorectal cancer that binds to the EFNB1 ligand." (PMID 27534621, 2016). "According to the latest investigations, it is not necessary for LOH to occur in APC in order for the initiation of colorectal cancer to take place." (PMID 24148210, 2013). "Using this model, we interrogated system behavior, which emerges from the states and state changes of protein sites, with the goal of elucidating the distinctive mechanisms by which APC and APC1338 regulate the rate of destruction in normal and SW480 colorectal cancer cells." (PMID 24086117, 2013). "The mechanism of regulation of β—catenin degradation by the destruction complex and the role of truncation of APC in colorectal cancer are not entirely understood." (PMID 24086117, 2013). "Together, our results indicate that truncated APC is required for the expansion of colorectal cancer cells in vitro, in line with a previous observation made in SW480 cells, and that truncated APC suppresses not only β-catenin signalling but surprisingly also its protein level." (PMID 22509309, 2012). "Therefore, tumors displaying β-catenin, APC or AXIN1 mutation are considered to display active or constitutive canonical Wnt signaling Activation of canonical Wnt signaling appears to be a common event for colorectal cancer, as opposed to HCC with mutations limited to a subset of these cancers." (PMID 19849855, 2009). "After verification using the colorectal cancer cell lines and having excluded a small number of samples with 5q copy number changes, 75/268 adenomas were both successfully analysed and showed LOH involving APC." (PMID 19515250, 2009). "Similarly, comparing the survival of colorectal cancer patients with PIK3CA, FBXW7 and APC mutations/CNVs to all other patients without each of these mutations, only patients with concurrent PIK3CA mutations and CNVs had poorer survival outcomes." (PMID 41415395, 2025). "Regardless of the APC gene mutation status, the results of CTC measurement using CK and Vim in all colorectal cancer patients also highlighted a stage-dependent increase in CTC number and frequency, with median CTC counts of 1, 2, 4, and 12 cells for Stages I, II, III, and IV, respectively." (PMID 39858085, 2025). "Sphingolipids have been shown to be reduced in patients with colorectal cancer, although some evidence suggested that this may not be due to APC knockout." (PMID 33620068, 2021). "Using genome-wide analysis of promoter methylation in 45 colorectal cancer cell lines, we found that higher overall methylation levels were associated with microsatellite instability (MSI), faster proliferation and absence of APC mutations." (PMID 33892786, 2021).
colorectal cancer (continued). "As we previously said, APC min/J mouse model is not totally representative of human colorectal cancer and it possesses notable differences, as the presence of small intestinal lesions, contrary to the majority of tumors being in the colon and rectum of familial adenomatous polyposis (FAP) patients." (PMID 32316101, 2020). "Several of our results support the Wnt enhanceosome model and, indeed, can be explained by it even though this model, derived from biochemical and functional data from Drosophila and human cells (including APC-mutant colorectal cancer cells) has not been validated specifically for murine cells." (PMID 30760710, 2019). "Analyses of data sets available in the Gene Expression Omnibus (GEO) also provide convincing evidence that β-CATENIN/TCF4 signaling does not increase expression of PPARB/D mRNA in colorectal cancer models, both in vivo and in vitro, including those with mutant APC or CTNNB1 genes." (PMID 31602402, 2019). "The concurrent presence of the mutated forms of APC and WAS was not specific to HB, it has been reported that dysregulation of WAS or APC relates to the onset and progression of other cancers, like decreasing WAS expression in chronic myeloid leukemia and APC mutant in colorectal cancer." (PMID 30619485, 2018). "Here, we quantify promoter methylation of ITF2 and APC by MethyLight in two case-case studies nested in population-based CRC cohorts from the Ontario Familial Colorectal Cancer Registry (n = 330) and the Newfoundland Familial Colorectal Cancer Registry (n = 102) comparing MSI status groups." (PMID 26884349, 2016). "In particular, the interactions between APC and β-catenin, FLII, ERBB2IP, or TPM1 have been validated; (iv) by using TAP system and MudPIT approach, Koch and coworkers have reported the interactors of c-Myc oncoprotein in colorectal cancer cells and embryonic kidney cells." (PMID 27011181, 2016). "It has been recently demonstrated that CDX2 regulates gene expression of APC and AXIN2, components of the β-catenin degradation complex, and increasing evidences indicate that CDX2 inhibits the activity of β-catenin and thereby the progression of the colorectal cancer." (PMID 26910375, 2016). "Indeed, there is cumulative evidence that pharmacologic neutralization of TNKS/2 activity proficiently (albeit not uniformly) impairs the growth of APC-mutant colorectal cancer cells by attenuating Wnt-mediated signals." (PMID 26787475, 2016). "While genetic mutations of certain components of the Wnt/β-catenin pathway, such as APC and CTNNB1, are significant contributing factors for colorectal cancers, they are typically not the predominate mechanism associated with many other types of cancer such as breast and prostate cancers." (PMID 22195040, 2011). "These syndromes, whilst easily characterisable, have a well understood sequence of genetic mutations that predispose the sufferer to developing colorectal cancer, initiated for example in FAP by the loss of the second, normal allelle of the tumour supressor APC gene." (PMID 19424478, 2008). "In 103 sporadic colorectal cancers no alterations were found in the K-ras, APC or hMLH1 genes." (PMID 16356174, 2005).
colorectal cancer (continued). "To explore whether APC might participate in the regulation of Wnt/β-catenin signaling after CDK11 depletion, we tested the effect of CDK11 depletion on Wnt/β-catenin signaling in two colorectal cancer cell lines: SW480 cells, whose APC was truncated, and HCT116 cells, whose APC was intact." (PMID 32587772, 2020). "Interestingly, the mother of the patients, also carrying the APC truncating mutation, has not exhibited any symptoms of FAP or colon cancer, but has a higher than normal risk of developing APC-related diseases, such as FAP and colorectal cancer." (PMID 30619485, 2018). "Importantly, seminal work published back-to-back in Science show APC mutant colorectal cancers fail to regulate β-catenin, which permit constitutive transcriptional activation of a β-catenin/TCF-4 complex, thus driving Wnt signalling in colorectal cancer tissue." (PMID 29570681, 2018). "For example, APC promoter methylation may be a potential biomarker for the carcinogenesis of colorectal cancer, SMAD4 expression was a prognostic marker for survival in colorectal cancer patients, and the overexpression of CXCR4 reduced overall survival in colorectal cancer patients." (PMID 27504822, 2016). "We investigated whether 18 common colorectal cancer (CRC) predisposition single-nucleotide polymorphisms (SNPs) could help to explain some cases with multiple adenomas who phenocopied FAP or MAP, but had no pathogenic APC or MUTYH variant." (PMID 24801760, 2015). "In fact, despite the attractiveness of the two-hit hypothesis, colorectal cancer is an important exception to the pattern among adult cancers, rather than the rule: APC is central to a dominant familial syndrome and frequently mutated somatically in the non-familial disease." (PMID 22675446, 2012). "The preliminary observation from the colorectal cancer cell lines that there might be a non-random distribution of mitotic recombination breakpoints between the chromosome 5 centromere (~50 Mb) and APC prompted us to examine this phenomenon in a larger set of tumours." (PMID 19515250, 2009). "APC-mutant HT29 and β-catenin–mutant HCT116 colorectal cancer cells with or without TCF7L2 knockout were obtained from the Hecht group (Albert Ludwigs University of Freiburg), and xenograft tumors were generated." (PMID 38488003, 2024). "In contrast, the APC mutant and KRAS WT COLO320DM colorectal cancer cell line did not reduce growth or change canonical WNT activity upon treatment with the MEKi, neither alone or in combination with the TNKSi." (PMID 30717152, 2019). "In the current review, the lack of specificity for one cancer was seen for methylated APC and RASSF1A that have prognostic potential in both gastric and colorectal cancers." (PMID 30087854, 2018). "GD82#1, affected by multiple polyposis and ciecum carcinoma, showed a lower level of APC expression; for GD82#2, presenting colorectal carcinoma without polyposis, the expression level for APC gene was higher." (PMID 26511139, 2015). "More specifically, our objective was to assess knowledge, attitudes, and educational needs of Italian residents related to the use of genetic tests for breast and colorectal cancer, particularly the BRCA1/2 and APC tests, irrespective of the field of specialization." (PMID 25050348, 2014). "APC-Asef interaction can relieve the negative intramolecular regulation of Asef, which leads to aberrant migration in human CRC, suggesting that this interaction might be a potential target for the treatment of invasive migration in colorectal cancer." (PMID 34691990, 2019).
Familial adenomatous polyposis (658 papers, 1994 to 2026). Familial adenomatous polyposis (FAP) is characterized by the development of hundreds to thousands of adenomas in the rectum and colon during the second decade of life. "Colorectal adenomatous polyposis resembling FAP can develop if the pathogenic variant in the APC gene occurs in cells that differentiate into colonic mucosal cells." (PMID 41214301, 2026). "Background/Objectives: Familial adenomatous polyposis (FAP) is an autosomal dominant disorder caused by pathogenic variants in the adenomatous polyposis coli (APC) gene." (PMID 41595623, 2026). "In hereditary forms of DTFs (5–10% of cases), a tumoral pathogenic variant in the APC gene is linked to conditions like familial adenomatous polyposis or Gardner’s syndrome activating the canonical Wnt/β-catenin signaling pathway." (PMID 39860616, 2025). "There are associations with familial adenomatous polyposis, Gardner syndrome and mutations in the adenomatous polyposis coli (APC) gene." (PMID 41228143, 2025). "Familial adenomatous polyposis (FAP) is the autosomal dominant hereditary polyposis syndrome caused by germline pathogenic or likely pathogenic variants in the APC gene." (PMID 41129004, 2025). "The genetic development of CRC often starts with an inactivating mutation of the APC gene, which is responsible for familial adenomatous polyposis (FAP)." (PMID 40310348, 2025). "Familial adenomatous polyposis (FAP) is a hereditary colorectal cancer syndrome caused by inactivating mutations in the Adenomatous Polyposis Coli (APC) gene." (PMID 40451978, 2025). "(ii) Familial Adenomatous Polyposis (FAP): FAP is caused by mutations in the APC gene and is characterized by the development of hundreds to thousands of polyps in the colon and rectum during adolescence." (PMID 41541272, 2025). "Somatic activating mutations in the CTNNB1 gene (Wnt/β-catenin pathway) are the predominant driver in sporadic DTs, whereas germline mutations in the APC (adenomatous polyposis coli) gene underline FAP (familial adenomatous polyposis) and Gardner syndrome." (PMID 41227209, 2025). "Familial adenomatous polyposis (FAP) is an autosomal dominant disorder caused by heterozygous P/LPV in APC, which interfere with the Wnt signalling pathway, disrupting several stages of cell development." (PMID 40361475, 2025). "A smaller proportion of cases are linked to germline mutations in the APC gene, predisposing patients with Familial Adenomatous Polyposis (FAP) to develop DTF; APC is involved in beta-catenin degradation and thus regulates free beta-catenin concentration." (PMID 39858074, 2025). "APC mutations, first linked to familial adenomatous polyposis (FAP), are found in 80% of colorectal adenomas and cancers." (PMID 40943055, 2025). "Individuals with familial adenomatous polyposis, involving germline APC mutations, develop multiple adenomas." (PMID 41285904, 2025). "Wnt dysregulation in thyroid tumors in patients with familial adenomatous polyposis is due to germline loss of function of APC (typically due to exon 15 mutations), typically followed by a somatic APC mutation as a second hit." (PMID 41175860, 2025). "Familial adenomatous polyposis (FAP) (OMIM #175100) described as a result of mutations of the adenomatous polyposis coli (APC) gene (OMIM #152230) have an autosomal dominant pattern of inheritance." (PMID 40225021, 2025). "Familial adenomatous polyposis (FAP) is an autosomal dominant disorder characterized by germline mutations in the adenomatous polyposis coli (APC) gene." (PMID 40702333, 2025). "Familial adenomatous polyposis (FAP) is an inherited autosomal dominant disorder caused by germline mutations in the adenomatous polyposis coli (APC) gene." (PMID 39944699, 2025).